TEX15 (testis expressed 15, meiosis and synapsis associated)
Description:
Required during spermatogenesis for normal chromosome synapsis and meiotic recombination in germ cells. Necessary for formation of DMC1 and RAD51 foci on meiotic chromosomes, suggesting a specific role in DNA double-stranded break repair (By similarity). Essential executor of PIWIL4-piRNA pathway directed transposon DNA methylation and silencing in the male embryonic germ cells (By similarity). PIWIL4-piRNA binds to nascent transposon transcripts and interacts with TEX15, which may in turn recruit the epigenetic silencing machinery to the transposon loci (By similarity). Not required for piRNA biosynthesis (By similarity).
Synonyms: CT42; SPGF25
Tractability: No criterion of Open Targets' tractability assessment is met for any kind of drug.
Gene: Protein-coding gene on chromosome 8 (30,831,544 to 30,913,008, reverse strand). Ensembl gene ENSG00000133863.
Subcellular location: Cytoplasm; Nucleus
Subcellular location (Human Protein Atlas): Cytosol; Nucleoplasm
Pathways (Reactome):
Reproduction: Meiotic recombination
Gene Ontology:
Biological process: DNA methylation-dependent constitutive heterochromatin formation; male meiotic nuclear division; piRNA processing; regulation of double-strand break repair via homologous recombination; synaptonemal complex assembly; transposable element silencing; homologous chromosome pairing at meiosis
Cellular component: cytoplasm; nucleus
Genetic constraint (gnomAD): Loss-of-function variants: 154 observed, 223.22 expected, observed/expected ratio (o/e) 0.69, 90% interval 0.6 to 0.79. The upper end of that interval is the gene's LOEUF score, 0.79, which puts it in group 3 of 6, group 1 being the genes least tolerant of losing a copy. Missense variants: 3,593 observed, 3,637.9 expected, observed/expected ratio (o/e) 0.99, 90% interval 0.96 to 1.01. Synonymous variants: 1,299 observed, 1,279.2 expected, observed/expected ratio (o/e) 1.02, 90% interval 0.97 to 1.06.
Homologues: Orthologues: chimpanzee TEX15 (99% identical), macaque TEX15 (91% identical), dog TEX15 (70% identical), rabbit TEX15 (66% identical), rat Tex15 (52% identical), mouse Tex15 (48% identical), tropical clawed frog tex15 (20% identical), zebrafish tex15 (1% identical).
Diseases named in the same sentence as TEX15 in open-access papers:
TEX15 is named in the same sentence as 14 diseases in open-access papers, as found by Europe PMC text mining. Sharing a sentence is not in itself a finding about the gene and the disease. The quoted sentences say what the papers report.
Azoospermia (6 papers, 2018 to 2023). Absence of any measurable level of sperm,whereby spermatozoa cannot be observed even after centrifugation of the semen pellet. "Biallelic mutations in two other DNA DBS repair genes, MCM8 and TEX15 were reported in azoospermia and oligo/crypto/azoospermia, respectively." (PMID 34501457, 2021). "Analysis of the genotype and allele frequencies of the TEX15 tagger variants comparing the severe oligozoospermia (SO) group against the non-obstructive azoospermia (NOA) group." (PMID 36589743, 2022). "Therefore, this study aimed to replicate this finding in humans byexamining the expression levels of TEX11, TEX12,TEX14, and TEX15 in the testis tissue of patients withnon-obstructive azoospermia and comparing them against controls." (PMID 29932616, 2018). "We expand earlier reports documenting heterogeneous allelic pathogenic TEX15 variants that cause a range of SPGF phenotypes from oligozoospermia (low sperm) to nonobstructive azoospermia (no sperm) with meiotic arrest and report the prevalence of 0.6% of TEX15 variants in our patient cohort." (PMID 37234866, 2023). "Among the five patients we used as controls, there were 2 non-obstructive azoospermia patients; C1 had a hemizygous stop-loss in MAGEB4 and C2 had a homozygous stop-gain in TEX15." (PMID 33809228, 2021). "Current examples are TEX15 and NPAS2 in non-obstructive azoospermia and ADGRG2 in obstructive azoospermia." (PMID 29527098, 2018).
breast carcinoma (4 papers, 2017 to 2024). "Curiously, TEX15 c.7253dupT and c.8325G > A behaved differently: the breast cancer associated TEX15 c.7253dupT mRNA was stable, whereas the transcript from the c.8325G > A allele was efficiently targeted by nonsense-mediated decay." (PMID 28386063, 2017). "The breast cancer associated TEX15 c.7253dupT differed from the other observed TEX15 mutation, c.8325G > A, in that it was stable at mRNA level whereas the c.8325G > A mRNA was efficiently degraded." (PMID 28386063, 2017). "Two different protein truncating mutations in the TEX15 gene showed potential association with breast cancer in the Northern Finnish cohort." (PMID 28386063, 2017). "Together with the observed association with breast cancer this indicates that the role of TEX15 extends beyond testis and meiosis-specific double-strand break repair." (PMID 28386063, 2017). "In addition, two deleterious TEX15 genetic variants, Q1631H and c.7253dupT, have been associated with a higher risk of developing prostate and breast cancer respectively, further supporting a role for TEX15 in tumorigenesis." (PMID 38596293, 2024). "Although most functions of TEX15 are unknown, evidence suggests that TEX15, as a new susceptibility gene, is associated with breast cancer." (PMID 35741727, 2022). "In addition, a rare variant Q1631H in DNA repair gene TEX15 is associated with prostate cancer risk and truncating variants in TEX15 were proved to be potential breast cancer risk factor." (PMID 31481019, 2019). "Another TEX15 truncating mutation (c.8325G > A, Trp2775Ter, rs146619272) was identified in 7/247 (2.8%) of the Northern Finnish hereditary cases and it showed a borderline association with breast cancer (p = 0.063, OR = 2.7 and 95% CI = 1.1–6.8)." (PMID 28386063, 2017). "TEX15 represents yet another potential breast cancer susceptibility gene from the DDR pathway." (PMID 28386063, 2017). "Besides introducing TEX15 as a putative new breast cancer predisposition gene, the current results can be of relevance for individuals suffering from idiopathic spermatogenic failure." (PMID 28386063, 2017). "The extensive case-control association analysis performed here for the rare, presumably deleterious alleles in genes encoding important players in the DDR pathway identified two potentially breast cancer predisposing mutations: TEX15 c.7253dupT and FANCD2 c.2715 + 1G > A." (PMID 28386063, 2017). "c.7253dupT in TEX15, encoding a DDR factor important in meiosis, associated with hereditary breast cancer (p = 0.018) and likely represents a Northern Finnish founder mutation." (PMID 28386063, 2017). "In conclusion, truncating variants in TEX15 and FANCD2 are potential breast cancer risk factors, warranting further investigations in other populations." (PMID 28386063, 2017). "Further screening of TEX15 c.8325G > A in the additional Helsinki and Tampere cohorts revealed several carriers in both hereditary cases and controls with similar frequencies, indicating that TEX15 c.8325G > A might not be a breast cancer risk factor or that the risk associated with it is low." (PMID 28386063, 2017).
Infertility (3 papers, 2023 to 2025). "This study aimed to optimize the lipid-based transfection of a lentiviral plasmid vector into SSCs by targeting the Tex15 gene, which is associated with infertility in humans, using CRISPR/Cas9." (PMID 40438407, 2025). "Tex15 mutations are known to impair double-strand DNA repair and cause infertility." (PMID 40438407, 2025). "Additionally, a mutation in exon 1 of the Tex15 gene has been associated with infertility in a Turkish family, leading to progressive sperm count reduction over time." (PMID 40438407, 2025). "Recessive loss-of-function (LOF) TEX15 mutations are associated with SPGF in humans and knockout male mice are infertile." (PMID 37234866, 2023). "Previously, it was proposed that TEX15 stabilizes DNA repair proteins at the time of recombination and in its absence, spermatocytes fail to develop, resulting in infertility." (PMID 37234866, 2023). "Here we report the prevalence and allelic heterogeneity of TEX15 variants associated with SPGF in a combined cohort of over 1,000 infertile men." (PMID 37234866, 2023).
prostate carcinoma (3 papers, 2017 to 2023). A carcinoma that arises from epithelial cells of the prostate gland. "Curiously, two of them had a father diagnosed with prostate cancer: one was confirmed as a TEX15 c.7253dupT carrier, the other was not available for testing." (PMID 28386063, 2017).
male infertility (2 papers, 2022 to 2023). The inability of the male to effect fertilization of an ovum after a specified period of unprotected intercourse. "Under this assumption, it is reasonable to assume that the common TEX15 polymorphisms affecting male infertility were associated with less extreme manifestations of SPGF, such as SO." (PMID 36589743, 2022). "Analysis of the genotype and allele frequencies of the TEX15 tagger variants comparing groups of male infertility against the unaffected control group." (PMID 36589743, 2022). "In this context, high-penetrance pathogenic variants in TEX15 have been widely linked to human male infertility due to spermatogenic impairment in different studies." (PMID 36589743, 2022). "In fact, TEX15-defficient murine models show reproductive system abnormalities, including male infertility, altered spermatogenesis, arrest of male meiosis, decreased male germ cell number, DSB repair anomalies, and reduced testis weight." (PMID 36589743, 2022).
Hereditary breast cancer (1 paper, 2017). Breast carcinoma that has developed in relatives of patients with history of breast carcinoma. "In total, four of the recurrent mutations showed significant (TEX15 c.7253dupT and FANCD2 c.2715 + 1G > A) or borderline association (TEX15 c.8325G > A and RNF168 c.640_644del5) with hereditary breast cancer in the Northern Finnish cohort." (PMID 28386063, 2017).
cancer (3 papers, 2016 to 2019). A tumor composed of atypical neoplastic, often pleomorphic cells that invade other tissues. "It is possible that this stable allele might disturb some of the normal cellular functions of TEX15, potentially relating to cancer predisposition, more severely than a complete null allele." (PMID 28386063, 2017). "A large number of CTAs showed preferential expression in cancer stem-like cells, including high expression of TEX15 in side population cells." (PMID 31481019, 2019). "Proteins involved in repairing the DSB generated during meiosis, such as Testis Expressed 15 (TEX15) and Disrupted Meiotic cDNA1 (DMC1), are also expressed in cancer." (PMID 27275820, 2016).
tumour (1 paper, 2023). "These contain known cancer-testis antigen genes (MEGA5, MEGA1, TEX15, PNMA5 and ROR1) and a number of new candidate genes (PAX2, NTN4, NTNG2 and PDE10A), these genes can be used as tumour markers or potential therapeutic targets with some clinical value." (PMID 37994961, 2023).
TEX15 also shares sentences with these, for which no sentence is quoted: bladder cancer (1 paper); Cryptozoospermia (1); Fanconi anemia (1); female infertility (1); spermatogenic failure (1); spermatogenic failure 25 (1).